IL6 (interleukin 6)
Diseases named in the same sentence as IL6 in open-access papers (continued):
Sharing a sentence is not in itself a finding about the gene and the disease.
sarcopenia (continued). "In addition, participants with a higher blood IL-6 status had an increased likelihood of having sarcopenia at 2.3 times compared to than those of a low IL-6 status [Adjusted OR: 2.3; 95% CI 0.80–6.40; Pfor trend < 0.05], after adjustments for age, and other body composition factors." (PMID 37161054, 2023). "However, due to the sedentary lifestyle of sarcopenia patients, the beneficial role of IL-6 may decrease, and the inflammatory effects may overwhelm the anti-inflammatory roles." (PMID 37577356, 2023). "Tumor necrotizing factor (TNF)-α, interleukin (IL)-1β, IL-6, and IL-15 levels were assessed at baseline for both groups and after a 12-week intervention consisting of resistive exercise and supplementation with branched-chain amino acids, calcium, and vitamin D3 in the patients with sarcopenia." (PMID 38032288, 2023). "Relevant studies show that the concentration of plasma inflammatory factors (IL-6 and TNF-α) is associated with the emergence of sarcopenia in men that is more prevalent than that in women, which may be caused by estrogen inhibiting the expression of inflammation-related genes." (PMID 36615879, 2023). "Moreover, recent evidence indicates that circulating IL6 is associated with frailty and sarcopenia in people younger than 75, but not in those ≥75." (PMID 36430485, 2022). "However, when stratified according to sarcopenia status, IL-6 was positively correlated with UGT among the sarcopenia group (r = 0.48, p-value < 0.05), and negatively correlated with TNF-α among the control group, respectively (r = −0.40, r = −0.45, p-value < 0.01)." (PMID 36291982, 2022). "Therefore, the present study explores the relationship between sarcopenia and IL-4, IL-6, IL-10, and TNF-α in the elderly population of agricultural and pastoral areas of Xinjiang, China, and is expected to lay a preliminary foundation for understanding its underlying mechanism." (PMID 36160136, 2022). "Regarding the mixed results observed in our study, CRP, but not IL-10 and TNF-α, significantly related to low physical performance, a systematic review and meta-analysis of 17 studies with 11,249 individuals also showed that only CRP, but not TNF-α and IL-6, is associated with sarcopenia." (PMID 35525916, 2022). "Furthermore, we did not observe any remarkable association between inflammatory biomarkers including IL-6 (OR 1.15; 95% CI 0.31–4.28), TNF-α (OR 0.68; 95% CI 0.17–2.77), and hs-CRP (OR 2.39; 95% CI 0.87–6.55) and the presence of sarcopenia even after controlling for plausible confounders." (PMID 35361818, 2022). "Increased inflammatory factors such as IL-6, resistin, TNF-α, and ROS production are also associated with NF-KB signaling and the ubiquitin-proteasome system in skeletal muscle, both of which may be involved in the pathogenesis of sarcopenia." (PMID 35250869, 2022). "Therefore, if we apply bDMARDS, which antagonizes TNF-α and IL-6, to inhibit inflammatory cytokine-induced proteolytic metabolism in a timely manner at an early stage of the disease, we can prevent the development of sarcopenia and OP." (PMID 35676311, 2022). "The changes in muscle fiber type and force observed in NSE/IL-6 transgenic muscle were also associated with signs of denervation and alteration of neuromuscular junction (NMJ), suggesting an alteration in the functional interplay between muscle and nerve, a typical feature of sarcopenia." (PMID 34359985, 2021). "Proinflammatory cytokines, such as interleukin (IL)-1, IL-6, and tumor necrosis factor alpha (TNF-α), cause skeletal muscle proteolysis by suppressing muscle genes and activating ubiquitin-proteasome-mediated proteolysis and are closely associated with both sarcopenia and cancer-related cachexia." (PMID 32828127, 2020).
sarcopenia (continued). "To date, TNF-α, IL-6, albumin and CRP have shown a relation with the development of low muscle strength or muscle mass over time, however, the current body of evidence fails to reveal a marker of chronic inflammation that is univocally associated with measures of sarcopenia in older people." (PMID 31455238, 2019). "Therefore, the catabolic effect of IL-6 is believed to promote protein imbalance over time, which may culminate in sarcopenia and low HGS." (PMID 31595206, 2019). "Furthermore, IL-6/IL-10 ratios were higher in subjects with sarcopenia (P < 0.05)." (PMID 30541467, 2018). "Moreover, higher ratios of IL-6/IL-10 were observed in the sarcopenia group (P < 0.05)." (PMID 30541467, 2018). "While IL-6 seems to be critically involved in hypoxia-induced adaptive changes in muscle metabolism it remains to be established whether these responses have also a defined role in the pathogenesis of sarcopenia." (PMID 28570949, 2017). "This study aimed to evaluate the correlation between inflammatory biomarkers such as C-reactive protein (CRP), tumor necrosis factor-alpha (TNF-α), interleukin-6 (IL-6), and the anabolic hormone insulin-like growth factor-1 (IGF-1) with sarcopenia." (PMID 42267078, 2026). "Elevated IL‐6 and GDF‐15 levels were significantly correlated with the presence of sarcopenia (p = 0.04 and p = 0.03, respectively)." (PMID 41380167, 2025). "Conversely, in sarcopenia, the levels of pro-inflammatory cytokines such as TNF- α and IL-6 are primarily elevated." (PMID 41226798, 2025). "It is also known that a chronic inflammatory milieu (high IL-6, TNF-α, interleukin-1 (IL-1), and C-reactive protein “CRP”) is correlated with sarcopenia in aging." (PMID 41348866, 2025). "Elevated levels of IL-6, CRP, and TNF-α have been investigated as possible pathophysiological mechanisms involved in sarcopenia." (PMID 41465572, 2025). "Inflammatory cytokines (e.g., TNF-α, IL-6) activate NF-κB and MAPK signaling pathways, exacerb muscle protein degradation and suppressing synthesis, thereby directly promoting sarcopenia." (PMID 41199827, 2025). "By elucidating the combined influence of IL‐6, GDF‐15 and sarcopenia on perioperative outcomes and long‐term survival, this study aims to enhance prognostication, optimise preoperative preparation and refine postoperative care strategies for patients with BC." (PMID 41380167, 2025). "The circulating factors in sarcopenia group were significantly lower: ALT, AST, ALB, γ-GT, CREA, UA, GLU, TG, LDL, GDF15, TNF-α and IL6." (PMID 40969368, 2025). "Interleukins exert a pivotal role in sarcopenia, with elevated TNF-α, IL-6, and IL-1β levels correlating with increased mortality and morbidity among older adults." (PMID 40429815, 2025). "In addition, IL‐6 secreted by adipose tissue might be involved in the pathogenesis of sarcopenia." (PMID 39764565, 2025). "This retrospective study investigates the roles of the biomarkers interleukin‐6 (IL‐6) and growth differentiation factor‐15 (GDF‐15), in the context of sarcopenia, assessing their impact on oncological and survival outcomes." (PMID 41380167, 2025). "Chronic systemic inflammation, characterized by elevated pro-inflammatory cytokines such as interleukin-6 (IL-6) and tumor necrosis factor-alpha (TNF-α), serves as a pivotal intermediary between sarcopenia and cardiovascular complications." (PMID 40142260, 2025). "Elevated levels of inflammatory cytokines, such as tumor necrosis factor-alpha (TNF-α), interleukin-6 (IL-6), and C-reactive protein (CRP), have been consistently observed in older adults with sarcopenia." (PMID 40283772, 2025). "ApoE4 status and plasma p-tau217 (AD), NfL (neurodegeneration), GFAP and IL-6 (inflammation), GDF-15 (senescence/sarcopenia) will be evaluated in all subjects (n = 1,662) both at the baseline and at the end of the study (12 months)." (PMID 40400914, 2025).
sarcopenia (continued). "To the best of our knowledge, we presented the first study showing the prognostic significance of IL‐6 and GDF‐15 in relation to sarcopenia and adverse outcomes in patients undergoing RC for BC." (PMID 41380167, 2025). "Research has identified elevated levels of pro-inflammatory cytokines such as interleukin-6 (IL-6), interleukin-8 (IL-8), tumor necrosis factor-alpha (TNF-α), and IL-1β in individuals with sarcopenia." (PMID 40943447, 2025). "Participants with sarcopenia, especially those with inflammation, had lower BMI and significantly higher CRP and IL-6 levels, highlighting the role of chronic inflammation in muscle deterioration." (PMID 40277851, 2025). "Growing evidence shows that serum levels of tumor necrosis factor (TNF)-α, interleukin (IL)-6, and C-reactive protein (CRP) are elevated in individuals with sarcopenia, typically reaching levels 2–4 times higher than those observed in younger controls." (PMID 40678078, 2025). "From the results, the network pharmacology analysis revealed the key mediating roles of IL-6 and TNF-α in the regulatory network of ECG, testosterone, and sarcopenia." (PMID 40724319, 2025). "Inflammation is a key contributor to sarcopenia, and proinflammatory cytokines such as TNF-α, IL-6, and IL-1 are frequently elevated in individuals with sarcopenia." (PMID 40589442, 2025). "In fact, elevated circulating levels of typical inflammaging mediators, such as Interleukin 6 (IL6), Tumor necrosis factor α (TNFα) and C-reactive protein (CRP), have been found in patients with sarcopenia." (PMID 38808117, 2024). "This study focused on randomized controlled trials (RCTs) that examined the effects of RT on interleukin-6 (IL-6), tumor necrosis factor-α (TNF-α), C-reactive protein (CRP), and interleukin-10 (IL-10) about sarcopenia." (PMID 38863698, 2024). "Suggested potential sarcopenia biomarkers are myostatin (MSTN), insulin-like growth factor 1 (IGF-I), C-terminal agrin fragment (CAF), interleukin-6 (IL-6), tumor necrosis factor alpha (TNF-α), and vitamin D." (PMID 39769198, 2024). "Elevated levels of IL-6, IL-1β, TNF-α, and CRP have been identified as potential contributors to the unfavorable outcomes of sarcopenia in PD-1 inhibitor treatment." (PMID 39101140, 2024). "Moreover, after reviewing the studies focusing on the relationships between cytokines, growth factors and sarcopenia, many factors, including IL1b, IL6, IL8, IL17 (interleukin‐17), TNFa, TGF1, GDF‐15 (growth differentiation factor‐15) and so on, may all relate to sarcopenia." (PMID 38556722, 2024). "In the future, the regulation of AChR-β by the IL-6/IL-6R-ERK1/2-PGC1α/MEF2C pathway should be investigated in patients and animals with sarcopenia." (PMID 39390392, 2024). "However, in our study, there was a lack of association between serum IL‐6 levels and sarcopenia." (PMID 38644163, 2024). "More specifically, among individuals with IBD, there is an upregulation TNF-α, IL-6, and interferon (IFN)γ, which all contribute to a higher overall systemic inflammatory burden and can lead to the development of sarcopenia." (PMID 38911683, 2024). "Research on chronic low-grade inflammation in the elderly has demonstrated that inflammatory cytokines such as IL-6 and TNF-α are significantly elevated in sarcopenia patients." (PMID 39556533, 2024). "Assessing IL-6 and IGF-1 as the primary biochemical markers of sarcopenia was driven by their accessibility in terms of measurement in Palembang." (PMID 38525752, 2024). "The proinflammatory factors TNF-α, IL-6, and MCP1 are reported to be involved in the inflammatory responses leading to the development of sarcopenia." (PMID 38873561, 2024). "Hence, IL-6 could be considered a clinical biomarker of sarcopenia and general frailty in patients." (PMID 37173873, 2023).
sarcopenia (continued). "The cytokine storm, with IL-6 and TNF-α, is the event that correlates the degree of inflammation to sarcopenia, creating a high potential for multiorgan damage, including in skeletal and cardiac tissue muscle." (PMID 36992190, 2023). "A growing body of literature highlights how pro-inflammatory cytokines, such as interleukin-6 (IL-6) and tumor necrosis factor-α (TNF-α), contribute to the process of protein homeostasis dysregulation and, consequently, to sarcopenia." (PMID 37173873, 2023). "BETs were found to coordinate the expression of genes associated with muscle atrophy through direct occupancy of catabolic genes by BRD2 and activation of the IL-6/AMPK/FoxO3 axis, leading to the development of sarcopenia." (PMID 37881635, 2023). "Of these inflammatory factors, C-reactive protein (CPR), interleukin-6 (IL-6) and tumor necrosis factor-a (TNF-a) are critical for predicting the incidence of sarcopenia." (PMID 36895911, 2023). "There are higher circulating levels of inflammatory cytokines such as interleukin-1 (IL-1), interleukin-6 (IL-6), C-reactive protein (CRP), and tumour necrosis factor-α (TNF-α), which lead to both tissue depletion and sarcopenia." (PMID 37077743, 2023). "Noteworthy, serum levels of IL-6 and TNF-α were significantly higher in sarcopenic patients, suggesting the role of these cytokines as inflammatory predictors of sarcopenia." (PMID 37238956, 2023). "The study discovered that patients with sarcopenia exhibit elevated levels of TNF-α, IL-1β and IL-6." (PMID 38032288, 2023). "For example, an increased plasma IL-6 and decreased IFN-γ has been observed in ageing mice as well as humans with muscle wasting diseases such as cancer cachexia and sarcopenia." (PMID 36830664, 2023). "Chronic, low-grade inflammation plays a central role in the progression of inflammaging and sarcopenia by modulating pro-inflammatory cytokines (TNF-α, IL-1, and IL-6." (PMID 36901121, 2023). "Em relação aos marcadores humorais e inflamatórios, não houve diferença significativa nas médias para os níveis séricos de PCR-as, IL-6, TNF-α, IGF-1 ou testosterona total entre os grupos com e sem sarcopenia ( Tabela 2 )." (PMID 37556651, 2023). "The GEE analysis adjusted by age and gender revealed sarcopenia significantly elevated TNF-α (p=0.003), IL-1β (p=0.001) and IL-6 (p<0.001), whereas intervention led to a decrease in TNF-α (p=0.005) and IL-1β (p=0.017) and an increase in IL-15 (p=0.024)." (PMID 38032288, 2023). "Subdividing the total population by considering the EASL sarcopenia criteria, there were statistically significant differences in BMI (p = 0.004), advanced HCC (p < 0.05), log (IL-6) (p = 0.031), lymphocytes (p = 0.005) and PMNs/lymphocytes ratio (p = 0.017)." (PMID 37173873, 2023). "Pro-inflammatory cytokines, such as interleukin-6 (IL-6) and tumor necrosis factor-α (TNF-α), contribute to the process of protein homeostasis dysregulation and, consequently, to sarcopenia." (PMID 37173873, 2023). "Our study result was in line with the previous animal and clinical studies, highlighting sarcopenia to be a pro-inflammatory status leading to elevated TNF-α, IL-1β, and IL-6." (PMID 38032288, 2023). "Firstly, it has been observed that patients with sarcopenia exhibit elevated levels of inflammatory cytokines such as TNF-α, IL-1β, and IL-6." (PMID 38032288, 2023). "Elevated C-reactive protein (CRP), IL-6, and TNF-alpha have shown the strongest correlation with sarcopenia and frailty, resulting in extreme muscle wasting due to the promotion of catabolic signals mediated through these proinflammatory cytokines." (PMID 36979712, 2023).
sarcopenia (continued). "In the Copenhagen sarcopenia study, elderly women also had significantly higher levels of CRP, TNF-α, and IL-6, compared with middle-aged women and significantly higher levels of CRP, TNF-α, IL-1β, and IL-4 compared with young girls." (PMID 36291982, 2022). "We found that the levels of inflammatory cytokines IL-6, IL-17A, and TNF-α were increased in sarcopenia patients, while the IL-10 level declined." (PMID 35237317, 2022). "Stress-induced activation of NF-κB leads to upregulation of different cytokines, including IL-6 and TNF-α, which play a crucial role in the pathogenesis of sarcopenia." (PMID 35276842, 2022). "In particular, high levels of IL-6 and TNF-α are directly correlated with sarcopenia and weakness in humans and mice." (PMID 35250869, 2022). "Our study performed a cross-sectional analysis of serum concentrations of IL-6, IL-10, IL-17A, and TNF-α in the context of sarcopenia in elderly individuals." (PMID 35237317, 2022). "In sarcopenia, an increased level of numerous proinflammatory cytokines, i.e., CRP, IL-6, IL-1β, and IL-8, are observed." (PMID 36364788, 2022). "In the present study, IL-6 was positively correlated with TUG, while CRP was positively correlated with TSF and inversely correlated with R-leg-M in the sarcopenia group only." (PMID 36291982, 2022). "IL-6, TNF-α, and CRP levels have been reported to be significantly upregulated in patients with sarcopenia." (PMID 35162870, 2022). "Systemic chronic inflammation and increased inflammatory markers such as CRP, IL-6, and TNF-α are related to increased muscle mass degradation and appearance of sarcopenia in ND-CKD patients." (PMID 35463026, 2022). "In this cross-sectional study, we aim to compare inflammatory factors levels, including IL6, CRP, and TNFα, between sarcopenia and non-sarcopenia in Iranian adults." (PMID 35361818, 2022). "The anti-inflammatory cytokines (such as IL-4, IL-10 and IL-15) can counteract the expression and activity of pro-inflammatory cytokines, especially IL-6 and TNF-α, to reduce muscle atrophy and delay sarcopenia." (PMID 36111339, 2022). "Conversely, two cytokines produced by muscles and protective towards NAFLD development—namely Interleukin 6 (IL6) and Irisin —seem to be reduced in sarcopenia." (PMID 35052859, 2022). "Sub-acute inflammation manifested by small but significant increases in levels of inflammatory biomarkers (e.g., IL-6 and TNF-α) has been reported with aging and sarcopenia." (PMID 35334853, 2022). "In line, a meta-analysis including 49 studies confirms that n-3 PUFA decreases the levels of IL-6 and CRP in middle-aged and older adults, thereby reducing the components of inflammageing, which contributes to sarcopenia." (PMID 35276842, 2022). "Various cytokines involved in the pathogenesis of sarcopenia have been identified in foreign studies and include TNF-α, IL-1, IL-2, IL-4, IL-6, IL-8, and IL-10." (PMID 36160136, 2022). "Neutrophil/lymphocyte ratio (NLR), tumor necrosis factor alpha (TNF-α), interleukin 6 (IL-6), C-reactive protein (CRP) are the markers most frequently associated with sarcopenic status and they could be considered as risk factors for the development of sarcopenia itself." (PMID 34944975, 2021). "Fortunately, studies have revealed the potential role of muscle-bone crosstalk involving myokines and osteokines, such as IL-6, irisin, myostatin, RANKL/RANK and osteocalcin, in the development of sarcopenia and osteoporosis in COPD." (PMID 34650518, 2021). "Secondly, increased levels of pro-inflammatory factors interleukin-6 (IL-6) and tumor necrosis factor-α (TNF-α) are reported in patients with sarcopenia and Alzheimer's cognitive impairment." (PMID 33714959, 2021). "The levels of IL-6, TNFa and CRP have been reported to be significantly up-regulated in sarcopenia patients." (PMID 33921004, 2021). "Increased levels of IL-6 and TNF-α and a reduced level of IL-10 have been reported in cases of sarcopenia." (PMID 34371826, 2021).